TNF (tumor necrosis factor)
Diseases named in the same sentence as TNF in open-access papers (continued):
Sharing a sentence is not in itself a finding about the gene and the disease.
osteosarcoma (continued). "To explore this, we determined the in vitro sensitivity of a panel of human osteosarcoma cell lines to GDC-0152 or LCL161, alone or with TNFα, using the “CellTiter-Glo” assay." (PMID 31521127, 2019). "Two minimally passed human osteosarcoma cell lines, OS9 and OS17, survived incubation with Smac mimetics as sole agents but responded to co-treatments with TNFα, like cells from most of the murine tumors we previously tested." (PMID 31521127, 2019). "TNF-α at 1 nM stimulates the lipoxygenase pathway, and 5-LOX metabolites including LTB4 and 5-HETE increase in human osteoblastic osteosarcoma cells." (PMID 25229347, 2014). "Table I shows the quantitative densitometry results from the effects of inducers PMA, TNF-α, IL-1β and LPS on MMP-2 and -9 secretion by osteosarcoma and rhabdomyosarcoma cell lines." (PMID 24190483, 2014). "A study analyzing osteosarcoma biopsies found that while CD8+ T cells were present in the TME, they lacked the ability to proliferate and secrete effector cytokines such as interferon-gamma (IFN-γ) and tumor necrosis factor-alpha (TNF-α)." (PMID 40170852, 2025). "Similarly, in osteosarcoma, TNF‐α‐loaded liposomes induced ICD in tumour cells, leading to TNF‐α‐triggered necrosis, tumour‐specific antigen release, enhanced DC activation, and T cell infiltration when combined with anti‐PD‐1/PD‐L1 therapy." (PMID 38594879, 2024). "By analyzing the KEGG enrichment results, we know that Radix Astragali acts on osteosarcoma through multiple signaling pathways, such as IL-17 signaling pathway, PI3K-Akt signaling pathway, TNF signaling pathway and PD-L1 expression and PD-1 checkpoint pathway in cancer." (PMID 38102307, 2023). "This study shows that luteolin may regulate multiple signaling pathways by targeting various genes like AKT1, STAT3, IL6, TNF, and VEGFA to inhibit osteosarcoma proliferation and metastasis." (PMID 37749554, 2023). "It was revealed that TNFα inhibits osteoblastic differentiation and maintains osteosarcoma cells in an undifferentiated state via the ERK pathway, and blocking TNFα could inhibit lethal tumor progression in vitro." (PMID 37749554, 2023). "To determine whether doxorubicin enhanced TNF-α, IL-6, IL-1β, TGF-β, and IFN-γ expression in osteosarcoma, we treated MG63 and 143B cells as indicated." (PMID 35326493, 2022). "Finally, we combined vMyx-hTNF with three test ICIs in combination therapies to show that TNF-armed MYXV can potentially synergize with standard immunotherapy to treat and even eliminate lung metastatic osteosarcoma." (PMID 34553039, 2021). "Of the three Smac mimetics that cooperated most potently with TNFα to kill osteosarcoma cells in vitro, LCL161 and GDC-0152 have progressed furthest towards clinical use, so they were selected for pre-clinical in vivo anti-osteosarcoma testing." (PMID 31521127, 2019). "Although these mice possess innate immune cells, which can produce the TNFα required for Smac mimetic-mediated osteosarcoma cell destruction, they have almost no T cells." (PMID 31521127, 2019). "Unlike some other cell types that can produce autocrine TNFα in response to Smac mimetic treatment, this class of drugs only killed osteosarcoma cells upon provision of exogenous TNFα." (PMID 31521127, 2019). "The presence of macrophages in spontaneously-arising osteosarcomas has been published, but to our knowledge the amount of TNFα within naturally-arising osteosarcomas have not previously been measured." (PMID 31521127, 2019). "Given that the NF‐κB subunits are often activated by TNF‐α in several cancer types, we sought to examine whether the TNF‐α‐mediated signaling pathway is activated in osteosarcoma cells." (PMID 29377600, 2018). "Taken together, our results support a model in which the activation of the TNF‐α/NF‐κB axis contributes to an increase in CRL4BDCAF11 activity and a decrease in p21Cip1 protein levels, thereby controlling cell cycle progression in human osteosarcoma cells." (PMID 29377600, 2018).
osteosarcoma (continued). "Thus, we answered the two key questions, and our results reveal the important role of the TNF‐α/NF‐κB axis in the regulation of CUL4B expression and cell cycle progression in human osteosarcoma cells." (PMID 29377600, 2018). "The observed overexpression of cIAP1/2 in osteosarcomas probably reflects selective pressure during tumorigenesis for TNFα to stimulate proliferation rather than cell death." (PMID 27129149, 2016). "Although the concentration of TNFα within osteosarcomas has not been reported, presumably the excess TNFα in the blood derives from the tumor site, implying that the intratumoral levels would be much higher." (PMID 27129149, 2016). "The IAP antagonists SM-164, GDC-0152 and LCL161, which efficiently target XIAP and cIAPs, sensitized cells from most osteosarcomas to killing by low levels of TNFα but not TRAIL." (PMID 27129149, 2016). "Murine osteosarcoma cells transfected with the VCP gene exhibited constant activation of NF-кB, rapid degradation of phosphorylated-inhibitor кBα, decreased apoptosis rates after tumor necrosis factor α stimulation, and increased metastatic potential." (PMID 27344168, 2016). "RIPK3 levels varied considerably between tumors and RIPK3 was not required for IAP antagonism to sensitize osteosarcoma cells to TNFα." (PMID 27129149, 2016). "Using human osteosarcoma, U2OS cells expressing ERβ as a model, Cvoro and colleagues showed that both estradiol and ERβ-selective agonists reduced the activation of 18 pro-inflammatory genes (including TNF-α, IL-6, and CSF2) induced by TNF-α." (PMID 25699240, 2015). "Similarly, TNF promotes neural stem (NSC) cell proliferation but inhibits their differentiation and maintains osteosarcomas in their undifferentiated state." (PMID 25223735, 2014). "Similarly, TNFα induced nuclear buildup of a HIF-1α-eGFP chimera protein in the HIF-1α_U2OS Redistribution assay based on an osteosarcoma cell line." (PMID 22355351, 2012). "The addition of TNF-α exhibits a synergistic anti-tumour effect, resulting in regression of the tumour in 54% and 100% of the cases for the BN175-fibrosarcoma and the ROS-1 osteosarcoma respectively." (PMID 10732774, 2000). "In addition, macrophages polarized in vitro with GM-CSF and further activated with MTP-PE and IFNγ are capable of inhibiting osteosarcoma growth by producing soluble factors, although independent of TNFα or IL-1β." (PMID 38919608, 2024). "Experimental results showed that luteolin could inhibit cell viability and significantly decrease the expression of AKT1, STAT3, IL6, TNF, and VEGFA, and luteolin could also inhibit osteosarcoma proliferation and metastasis in osteosarcoma orthotopic mouse model." (PMID 37749554, 2023). "Recently, oncolytic virotherapy using MYXV armed with human Tumor Necrosis Factor (vMyx-hTNF) delivered systemically by leukocyte carrier cells was used alone and in combination with immunotherapy in the luciferase-tagged K7M2 lung metastatic osteosarcoma model." (PMID 35053501, 2022). "Interestingly, B cells in TNF‐Tg SBM also show increased levels of C‐type lectin domain family gene CLEC4D and CLEC4E, suggesting that the CLEC11A+ B cells in osteosarcoma may have similar biological functions as the TNF‐Tg SBM‐derived B cells." (PMID 36305631, 2022). "Besides, infection upregulates the cytokine secretion of inflammatory macrophages, including tumor necrosis factor-α (TNF-α) and interferon-γ (IFN-γ), and reactivate the immune system towards anti-tumor response to attenuate immunosuppression induced by osteosarcoma." (PMID 33363016, 2020). "Previous work revealed that cells from murine osteosarcomas were efficiently sensitized by physiologically achievable concentrations of some Smac mimetics (including GDC-0152 and LCL161) to killing by the inflammatory cytokine TNFα in vitro, but survived exposure to Smac mimetics as sole agents." (PMID 31521127, 2019).
osteosarcoma (continued). "Levels of TNFα within osteosarcomas have not been previously reported, but published data suggest that they may be high." (PMID 31521127, 2019). "Serum TNF levels were not correlated with the occurrence of osteosarcoma." (PMID 28955228, 2017). "In vitro, the combination of TNF-α and melphalan did not result in a synergistic growth-inhibiting effect on CC 531 colon adenocarcinoma cells, whereas an additive effect was observed on osteosarcoma ROS-1 cells." (PMID 10027309, 1999). "Additionally, chemotherapy‐induced apoptosis of hematopoietic stem cells in osteosarcoma patients may be promoted by factors such as IFN‐r and TNF‐α, triggering biochemical reactions in target cells, including elevated calcium ion levels, DNA degradation, and apoptosis." (PMID 39621534, 2024). "Similarly, results of a recent study showed that, in the osteosarcoma model, co-treatment with LCL161 and doxorubicin is particularly effective, impeding primary tumor growth and delaying or preventing metastasis; however, it only efficiently kills osteosarcoma cells when TNFα is supplied in vitro." (PMID 32325691, 2020). "Therefore, serum TNF levels were not correlated the occurrence of osteosarcoma." (PMID 28955228, 2017). "In contrast, studies in highly invasive tumors such as osteosarcoma and malignant glioma have not reported activation of EGFR/MAPK by fibulin-3 but have shown instead direct activation of canonical TNF-alpha/NF-κB signaling." (PMID 36303838, 2022). "Notably, the cytokine TNFα, which is related to osteosarcoma progression, could reduce the phosphorylation of CBX4 at T437 to increase CBX4 expression in cells, suggesting that the phosphorylation of CBX4 at T437 by CK1α is relevant to the development of osteosarcoma." (PMID 32111827, 2020).
disc degeneration (101 papers, 2009 to 2025). "Previous literature shows an increased amount of TNF-α mRNA and higher serum levels of TNF-α to be associated with inflammation as well as the progression of disc degeneration." (PMID 37371064, 2023). "Owing to the ability of digoxin to counteract TNF-α-induced disc degeneration, we then sort to determine the underlying mechanism." (PMID 37790932, 2023). "Animal models of disc degeneration/injury have identified that the increased proportion of proinflammatory M1 macrophages due to greater TNF expression is significantly associated with fat and connective tissue accumulation in MM." (PMID 36918849, 2023). "In summary, plasma IL-6 and TNF-α concentrations were positively correlated with the degree of lumbar disc degeneration, and this association was most pronounced in the upper lumbar discs." (PMID 35096205, 2022). "As prior studies have implicated inflammatory cytokines such as TNF-α in the development of paraspinal muscle pathology in the setting of disc degeneration [20,], we sought to characterize the macrophage density among muscle fibers." (PMID 35141626, 2021). "In an animal model of intervertebral disc degeneration, TNFα signaling contributed to disc degeneration by inducing apoptosis through caspase 3, and that subsequent disc degeneration caused pain." (PMID 34938263, 2021). "Intradiscal injection of TNF‐α in a porcine model was sufficient to induce early‐stage disc degeneration, characterized by matrix loss, annular fissure formation, and vascularization." (PMID 33015577, 2020). "In summary, while elevated systemic TNF-α is insufficient to promote disc degeneration in intact discs, it predisposes mice to spontaneous herniation." (PMID 30584238, 2018). "Inflammation is the main pathological process associated with disc degeneration, and TNF-α, as a typical inflammatory cytokine, plays a crucial role in inflammatory cytokine-induced disc degeneration." (PMID 29941029, 2018). "In addition, activation of the TNF signaling pathway can increase the sensitivity of inflammatory cells and neurons to painful stimuli, leading to pain associated with disc degeneration." (PMID 39430414, 2024). "Furthermore, TNF-α levels are closely associated with clinical conditions such as LBP and anti-TNF-α treatment can decrease the progression of disc degeneration and alleviate symptoms of LBP." (PMID 37239908, 2023). "Moreover, the loss of DHI and the grade of disc degeneration become more serious at 4 and 6 weeks in the TNFα-NPC-Exo groups." (PMID 35359595, 2022). "In addition, we have demonstrated that the antioxidant NAC treatment can delay the disc degeneration caused by Bmi‐1 deficiency or IL‐1β and TNF‐α stimuli." (PMID 32583517, 2020). "Even though both IL-1β and TNF-α could be implicated in the pathogenesis of disc degeneration, IL-1β could be a better therapeutic target for IVD regeneration." (PMID 24278441, 2013). "TNF-α and IL-1β are involved in initiation and progression of disc degeneration by regulating the inflammatory response, senescence, apoptosis, and matrix destruction." (PMID 40244065, 2025). "For instance, IL6 and TNF are well-documented mediators of inflammation and pain in disc degeneration." (PMID 40722613, 2025). "TNF can exacerbate disc degeneration by promoting the expression of matrix metalloproteinases (MMPs) and other catabolic enzymes that degrade the extracellular matrix of the disc." (PMID 40722613, 2025). "TNF-α activates the NF-κB signaling pathway, accelerating extracellular matrix breakdown, promoting cellular apoptosis, and contributing to progressive disc degeneration." (PMID 41010665, 2025). "During disc degeneration, immune cell infiltration leads to the release of pro-inflammatory cytokines such as tumor necrosis factor-alpha (TNF-α), interleukins IL-1β, IL-6, and IL-17, initiating and perpetuating a degenerative cascade." (PMID 40806719, 2025).
disc degeneration (continued). "A small number of studies have found that M2 macrophage‐conditioned medium inhibits disc degeneration in an environment enriched with TNF‐α." (PMID 40371270, 2025). "The sustained elevation of IL-6 and TNF-α levels in the IVDDG group at week five indicates that the healing process for disc degeneration is insufficient and ongoing." (PMID 40606908, 2025). "TNF-α and IL-1β contribute to disc cell aging, extracellular matrix degradation, and disc degeneration." (PMID 40244065, 2025). "Pro‐inflammatory M1 macrophages exacerbate disc degeneration by amplifying inflammatory cytokines (e.g., TNF‐α, IL‐1β), promoting cellular senescence, and stimulating abnormal angiogenesis and neural ingrowth." (PMID 40371270, 2025). "Recent studies indicate that TNF-α increases disc cell death by inducing oxidative stress and is positively correlated with the severity of disc degeneration." (PMID 40688090, 2025). "Rapamycin treatment decreased the gene expression of MMP-3, MMP-13, IL-1β, IL-6, TNF-α, and protein levels of P16 and P21 in bleomycin-treated AFSCs suggesting that potential of rapamycin for disc degenerative diseases." (PMID 40727644, 2025). "Data from animal models characterized by disc degeneration or lesions showed that elevated TNF expression in the adipose and connective tissues of the paravertebral muscles was significantly associated with the polarization of pro-inflammatory macrophages." (PMID 40224631, 2025). "Inflammatory cytokines such as TNF-α, IL-1β, and IL-6 are known to promote disc degeneration by enhancing matrix degradation and inflammatory responses." (PMID 40467648, 2025). "Recent research highlights how immune cells such as macrophages, T cells, and B cells, along with cytokines like IL-1β, TNF-α, and IL-6, play dual roles in both exacerbating and potentially mitigating disc degeneration." (PMID 40688090, 2025). "Recent studies have emphasized the role of inflammatory cytokines like IL-6 and TNF-α, which are not only markers of inflammation but also active contributors to disc degeneration." (PMID 40688090, 2025). "Inflammatory cytokines, especially TNF-α and IL-1β, are known as key mediators in the progression of disc degeneration." (PMID 40244065, 2025). "Inflammation is a critical driver of disc degeneration, characterized by elevated levels of pro-inflammatory cytokines such as IL-1β, TNFα, and IL-6, which exacerbate ECM degradation through the upregulation of matrix-degrading enzymes (MMPs, aggrecanases)." (PMID 40305345, 2025). "Recently, administration of the AdipoR agonist AdipoRon was found to effectively reduce the levels of the pro-inflammatory factor tumor necrosis factor α (TNF-α) and mitigate disc degeneration." (PMID 38532900, 2024). "Previous studies have shown a close relationship between disc degeneration and the TNF signaling pathway, a pro‐inflammatory cytokine that plays an important role in disc degeneration." (PMID 39430414, 2024). "Studies have shown that activation of the TNF signaling pathway is involved in the onset and progression of disc degeneration." (PMID 39430414, 2024). "The outcomes revealed the efficacy of Glycitin in protecting against disc degeneration in HNPCs by inhibiting TNF-α-mediated mitochondrial dysfunction." (PMID 38019477, 2023). "TNF-α and IL-1β levels have been positively correlated with the degree of severity of disc degeneration." (PMID 37206531, 2023). "In the degenerative nucleus pulposus, the TNF-α levels were markedly increased, and were positively related to disc degeneration level." (PMID 38019477, 2023). "The most commonly used method for inducing disc degeneration is by using single factors such as inflammatory factors (e.g., IL-1 and TNF-a), intermittent cyclic tension, or TBHP, applied to the NP or chondrocytes." (PMID 38192334, 2023).